ENSG00000259900 (novel protein)
Gene: Protein-coding gene on chromosome 16 (69,335,276 to 69,351,730, reverse strand). Ensembl gene ENSG00000259900.
Genetic constraint (gnomAD): Missense variants: 209 observed, 226.99 expected, observed/expected ratio (o/e) 0.92, 90% interval 0.82 to 1.03. Synonymous variants: 78 observed, 83.72 expected, observed/expected ratio (o/e) 0.93, 90% interval 0.77 to 1.12.